MIR518C (microRNA 518c)
Synonyms: hsa-mir-518c; MIRN518C
Gene: MicroRNA gene on chromosome 19 (53,708,735 to 53,708,835, forward strand). Ensembl gene ENSG00000283490.
Gene Ontology:
Biological process: miRNA-mediated post-transcriptional gene silencing
Homologues: Orthologues: chimpanzee ptr-mir-518c (97% identical). Paralogues in human: MIR518D (79% identical), MIR518F (77% identical), MIR516A1 (76% identical), MIR518E (76% identical), MIR523 (76% identical), MIR516A2 (75% identical), MIR522 (75% identical), MIR519C (74% identical), MIR520C (74% identical), MIR516B1 (73% identical), MIR518B (73% identical), MIR519A2 (73% identical), and 12 more.